ADAMTS13 (ADAM metallopeptidase with thrombospondin type 1 motif 13)
Diseases named in the same sentence as ADAMTS13 in open-access papers (continued):
Sharing a sentence is not in itself a finding about the gene and the disease.
atypical hemolytic-uremic syndrome (18 papers, 2011 to 2025). A rare, genetic thrombotic microangiopathy due to dysregulation of the alternative complement pathway and characterized by the triad of hemolytic anemia, thrombocytopenia, and acute renal dysfunction. "Since no genetic background was identified to be associated with the enzyme deficit, the diagnosis to be made in our patient was idiopathic TTP-HUS due to combined (autoantibody-mediated) ADAMTS-13/factor H deficiency." (PMID 22206706, 2011). "Here, we report a 17-year-old woman who presented with idiopathic combined autoantibody-mediated ADAMTS-13/factor H deficiency." (PMID 22206706, 2011). "The coincidence of combined ADAMTS-13/factor H deficiency confirms the presence of TTP-HUS." (PMID 22206706, 2011). "TMA can be classified according to its pathophysiology into: ADAMTS-13 deficiency-mediated, as in TTP and thrombocytopenia-associated multiple organ failure (TAMOF); complement-mediated, as in atypical HUS; and Shiga toxin-mediated." (PMID 38808867, 2024). "Hereditary ADAMTS13 deficiency is associated with fetal loss, preeclampsia, HELLP syndrome, TTP, or atypical hemolytic uremic syndrome." (PMID 28791286, 2017). "In our group, atypical hemolytic uremic syndrome (aHUS) was diagnosed in a 4-year-old girl (case 3) along with cerebral vasculitis and pulmonary embolism, with no ADAMTS-13 factor detected." (PMID 37626703, 2023). "Markedly decreased ADAMTS13 activity, the presence of Shiga-toxin-producing Escherichia coli (STEC) and abnormality of the complement system are useful for the diagnosis of TTP, STEC-hemolytic uremic syndrome (HUS)and atypical HUS, respectively." (PMID 30008620, 2018).
hypercoagulability (18 papers, 2015 to 2026). "An imbalance in the VWF antigen (VWF:Ag)/ADAMTS13 activity (ADAMTS13:AC) ratio was reported to be associated with angiogenesis and hypercoagulability as well as prognosis in patients with various types of cancer, especially those receiving chemotherapy." (PMID 40699668, 2025). "ADAMTS-13 and vWF are associated with the severity of LC via hypercoagulability, which represents a significant risk factor for PVT development." (PMID 38473925, 2024). "A study showed imbalance between alteration of the VWF‐ADAMTS13 axis and elevated Von Willebrand factor antigen to ADAMTS13 activity ratio COVID‐19 patients that enhances risk of micro thrombosis and hypercoagulation." (PMID 35168674, 2022). "In brief, TTP is a hypercoagulable state, caused by inhibition of ADAMTS-13, a factor-cleaving protease, by auto-antibodies which leads to a lack of degradation of von Willebrand factor multimers." (PMID 30073173, 2018). "The main factors contributing to occurrence or recurrence of TTP during pregnancy are a hypercoagulable state and progressive deficiency of ADAMTS13 over the course of gestation." (PMID 28443948, 2017). "In this study we show for the first time an in vivo association between hypercoagulability and an increased vWF antigen to ADAMTS13 ratio, platelet aggregates in intrahepatic portal vessels and decline in natural anticoagulants." (PMID 28839178, 2017). "In this study, a key independent event implicated in early hypercoagulability was a reduction in ADAMTS-13, which preceded the fall in the pro-coagulants (FV, FVIII) synthesised by the liver and occurred in the face of normal vWF Ag concentrations." (PMID 28839178, 2017). "Even though the deficiency of ADAMTS13 might induce hypercoagulability and result in cardiovascular diseases in HD patients, the other mechanisms are remained to be clarified." (PMID 34819564, 2021). "Studies suggest that the imbalance between ADAMTS13 and VWF is associated with angiogenesis and hypercoagulability and that this is important for cancer prognosis." (PMID 40699668, 2025). "Based on our results, we believe that the imbalance between ADAMTS13 enzyme and VWF substrate is directly associated with the pathophysiology of LC via hypercoagulability, and that Et-induced LC progression was also directly involved in liver injury." (PMID 35407443, 2022). "In summary, the results of our study indicate that ADAMTS13: AC, VWF: Ag, and Et are interrelated and associated with the severity of LC via hypercoagulability." (PMID 35407443, 2022). "Thrombophilia associated with vWF, FVIII, and FV is the result of an impaired turnover of these proteins, which favors the factors’ synthesis, due to an alteration in natural inactivators, such as ADAMTS13 for vWF and APC and PS for FVIII and FV, respectively." (PMID 35955419, 2022). "In conclusion, ADAMTS13, VWF, and Et may be interrelated and associated with the severity of LC via hypercoagulability." (PMID 35407443, 2022). "In a previous study, we have described the association between VWF, ADAMTS13, and D-Dimer with different levels of renal dysfunction in DM1 patients and we have raised the hypothesis that inflammation could be associated with hypercoagulability in patients with diabetic nephropathy." (PMID 26770985, 2016). "Patients who developed postoperative complications such as thrombophilia or new-onset bleeding had lower postoperative ADAMTS13 levels than those without complications." (PMID 40725629, 2025). "Our research group have previously studied these hemostatic markers in the same group of patients before renal transplantation and showed that the imbalance between ADAMTS13 and VWF levels may contribute to the hypercoagulability state." (PMID 26229221, 2015). "Moreover, the imbalance between ADAMTS13 enzyme and VWF substrate also reflects hypercoagulability." (PMID 35407443, 2022).
coagulopathy (17 papers, 2014 to 2025). "Second, we did not assess the levels of vWF and its multimer which directly affects coagulation associated with ADAMTS13 in this study, so we need to examine them to clarify the pathogenesis of the association between ADAMTS13 and trauma-induced coagulopathy." (PMID 33712048, 2021). "Regarding trauma, in a pediatric study, ADAMTS13 decreased with vWF elevation, which was associated with coagulopathy and endothelial cell injury." (PMID 33712048, 2021). "In critically ill patients with a coagulopathy, plasma transfusion reduced shedding of vWF and syndecan-1 from the endothelium, which was associated with increased levels of ADAMTS-13." (PMID 33336308, 2020). "In addition to TF, most other EV‐linked coagulopathy markers, including vWF, uPAR and ADAMTS13, also correlated with D‐dimer, length of hospitalization and age in both LEVs and SEVs." (PMID 34262673, 2021). "Using a controlled cortical impact mouse model, we demonstrated that the acrolein scavenger phenelzine prevented TBI-induced coagulopathy and recombinant ADAMTS-13 prevented acrolein-induced coagulopathy by cleaving von Willebrand factor (VWF)." (PMID 33939120, 2021). "Here we evaluate VWF/ADAMTS13 axis changes that suggest an early endothelial-based coagulopathy along with imbalanced plasma thrombin and plasmin generation." (PMID 35087853, 2021). "Similarly, the regulation of ADAMTS13 by lncRNAs presents new opportunities for exploring gene regulation mechanisms in coagulation disorders." (PMID 40699668, 2025). "Severe trauma patients with ADAMTS13 activity reductions might experience complications from coagulopathy." (PMID 33712048, 2021). "In this model of trauma-induced coagulopathy and organ failure, ADAMTS-13 given as an adjunct therapy to resuscitation resulted in earlier shock reversal, improved platelet-driven coagulation as assessed by ROTEM, decreased endothelial damage, and partially reduced organ inflammation." (PMID 33336308, 2020). "The present study showed that the ratio of VWF/ADAMTS13 increased significantly after the AAA surgery, which may indicate increasing risk of prothrombotic coagulation disorder." (PMID 25960882, 2014). "Furthermore, increased coagulopathy indicators correlated with low ADAMTS13 activity." (PMID 38608066, 2024). "Furthermore, the decreased ADAMTS13 activities on day 0 were improved over time, which was most likely due to transfusion of FFP for the treatment of coagulopathy after trauma." (PMID 33712048, 2021).
renal failure (16 papers, 2010 to 2024). "This anti-thrombotic mechanism would protect the normal kidney during inflammation and could also explain why most patients with ADAMTS13 deficiency do not develop severe kidney failure." (PMID 28139439, 2017).
atherosclerosis (15 papers, 2013 to 2025). A disease characterized by the build-up of fatty material and calcium deposition in the arterial wall resulting in partial or complete occlusion of the arterial lumen. "Although decreased ADAMTS13 activity and increased VWF level increase the risk of atherosclerosis, most scholars believe that ADAMTS13 and VWF level were two independent risk factors." (PMID 34276770, 2021). "The role of vWF and ADAMTS13 in atherosclerosis has also been recently proven in low-density lipoprotein receptor-deficient mice crossed with mice deficient for ADAMTS13, who were then treated with recombinant ADAMTS13." (PMID 34681830, 2021). "The VWF/ADAMTS13 axis is implicated in the pathogenesis of atherosclerosis, promoting plaque formation and inflammation through macrophage and neutrophil recruitment in inflamed lesions." (PMID 28634421, 2017). "Thus, patients with both immune and congenital TTP, who share a phenotype of partial or complete ADAMTS13 deficiency, develop accelerated vascular aging and atherosclerosis that predominantly affects the cerebral circulation." (PMID 37762903, 2023). "Studies have reported reduced ADAMTS13 activity or elevated VWF/ADAMTS13 ratios in young patients with atherosclerosis, including those with PAD." (PMID 41009700, 2025). "ADAMTS13 is probably the most important enzyme modulating hemostasis by preventing low grade thrombogenesis and inhibiting progressive atherosclerosis." (PMID 36359229, 2022). "The VWF/ADAMTS13 axis connection (bolded) is connected to dementia, mental disorders, autoimmunity, and atherosclerosis, are particularly interesting since changes in this axis appear to regulate vascularization and inflammation." (PMID 33946285, 2021). "Previously, experimental studies have identified a protective role for ADAMTS13 during the progression of atherosclerosis." (PMID 28591212, 2017). "Moreover, atherosclerosis is accelerated and adhesion molecule expression is increased with genetic deletion of ADAMTS13 which cleaves VWF at the A2 domain and removes it from the endothelial surface." (PMID 38693516, 2024). "The potential mechanism for these findings is that lower ADAMTS13 levels lead to an accumulation of larger, more physiologically active von Willebrand factor multimers that promote platelet activation, complement activation, and accelerate atherosclerosis." (PMID 37762903, 2023). "Thus, the sufficient level of ADAMTS13 restrains progressive atherosclerosis and maintains good vascular health of an individual for the long term and also prevents unnecessary thrombogenesis of both microthrombosis and combined micro-macrothrombosis." (PMID 36359229, 2022). "A second possible reason is that ADAMTS13 activity accelerates atherosclerosis." (PMID 34690744, 2021). "Also, ADAMTS13 indirectly modulates atherosclerosis by cleaving UL-VWF multimers that may actively participate in the macrophage and neutrophil recruitment in inflamed plaques, with a potential protective effect on atherosclerotic lesion progression." (PMID 28634421, 2017). "In animal models, lack of ADAMTS13 was found to promote the formation of plaques and vascular inflammation by generating signals for recruitment and extravasation of monocytes in the early stages of atherosclerosis, which are the pathological changes associated with CSVD." (PMID 34690744, 2021).
Arterial thrombosis (14 papers, 2016 to 2025). The formation of a blood clot inside an artery. "It has been previously shown that low ADAMTS13 plasma levels are associated with an increased risk of arterial thrombosis, including cerebrovascular disease." (PMID 36142883, 2022). "Many studies have reported an imbalance between VWF and ADAMTS13 in patients with arterial thrombosis, while several studies have also suggested a pathogenic role for ADAMTS13 in VTE." (PMID 34276770, 2021). "It is acknowledged that DDP-4 inhibitor, linagliptin has been associated with arterial thrombosis through mechanisms involving ADAMTS13 and oxidative stress." (PMID 33328991, 2020). "It has been shown that low levels of ADAMTS13 are associated with increased risks of arterial thrombosis." (PMID 31768485, 2019). "In previous literature, miR-103a-3p has known targets with VWF, miR-145-5p is associated with arterial thrombosis and smooth muscle proliferation, as well as ADAMTS13 levels, and miR-27b-3p, miR-320a/b-3p, and miR-424-5p are associated with venous thromboembolism." (PMID 39237986, 2024). "Further work is needed to determine the practicality of using ADAMTS13 for preventing and treating arterial thrombosis." (PMID 31768485, 2019). "Several in vivo studies have demonstrated that a reduction of ADAMTS13 activity can affect the development of arterial thrombosis." (PMID 27802307, 2016). "A role for ADAMTS13 in the pathogenesis of arterial thrombosis has been suggested." (PMID 27802307, 2016). "The ability of GoF ADAMTS‐13 to dissolve VWF–platelet agglutinates was examined with an assay of ristocetin‐induced platelet agglutination and in parallel‐flow models of arterial thrombosis." (PMID 30152919, 2018).
Cirrhosis (14 papers, 2011 to 2026). A chronic disorder of the liver in which liver tissue becomes scarred and is partially replaced by regenerative nodules and fibrotic tissue resulting in loss of liver function. "In hepatic cirrhosis, impaired ADAMTS13 production in hepatic stellate cells is thought to cause reduced ADAMTS13:AC." (PMID 38003518, 2023). "Patients with cirrhosis with detectable ADAMTS13:INH had higher Et levels than those with undetectable ADAMTS13:INH." (PMID 35407443, 2022). "The results of our study show that as cirrhosis progressed, ADAMTS13:AC levels gradually decreased, while VWF:Ag levels gradually increased." (PMID 35407443, 2022). "Patients with cirrhosis with high Et levels had lower and higher ADAMTS13:AC and VWF:Ag levels, respectively, than those with low Et levels." (PMID 35407443, 2022). "Several reports showed a decrease of ADAMTS13 activity either in cirrhosis or in plasma of patients with viral or alcohol hepatitis." (PMID 33805340, 2021). "Elevated thrombin generation capacity and an unbalanced ratio between von Willebrand factor and its cleaving protein (ADAMTS13) have recently been described in cirrhosis." (PMID 33000389, 2020). "The control group in our study exhibited significantly higher mean ADAMTS-13 levels than either of the groups of patients with cirrhosis." (PMID 29849584, 2018). "vWF is cleaved by the protease ADAMTS13 (a disintegrin-like and metalloprotease with thrombospondin type 1 motif 13), which is mainly synthesized in the liver and found to be reduced in cirrhosis." (PMID 25397410, 2014). "However, when corrected for total VWF:Ag, ADAMTS13-cleaved VWF was increased in patients with stable cirrhosis but was comparable to controls in the other patient groups." (PMID 41035784, 2025). "The VWF:Ag/ADAMTS13:AC predicted prognosis in patients with cirrhosis with ACLF." (PMID 36829443, 2023). "ROC analysis showed that the area under the ROC curve of AFP, DCP, AFP-L3%, VEGF, VEGFR2, ADAMTS13:AC, VWF:Ag, and the VWF:Ag/ADAMTS13:AC ratio for the early diagnosis of HCC in patients with cirrhosis was 0.61, 0.58, 0.54, 0.74, 0.67, 0.59, 0.67, 0.63, and 0.73, respectively." (PMID 31638892, 2019). "Our study showed that ADAMTS13 : AC decreased with increasing severity of cirrhosis." (PMID 21994870, 2011). "The VWF:Ag/ADAMTS13:AC increased according to the progression of ACLF in patients with cirrhosis and predicted prognosis in patients with cirrhosis with ACLF." (PMID 36829443, 2023). "A previous study reported that ADAMTS13 activity (ADAMTS13:AC) and VWF antigen (VWF:Ag) are predictive biomarkers of ACLF development in patients with cirrhosis." (PMID 36829443, 2023). "The mechanism responsible for the decrease in ADAMTS13:AC in patients with advanced cirrhosis may include enhanced consumption due to the degradation of large quantities of VWF, inflammatory cytokines, and/or ADAMTS13 plasma inhibitors." (PMID 38003518, 2023).
Disseminated intravascular coagulation (14 papers, 2013 to 2025). Disseminated intravascular coagulation is characterized by the widespread activation of coagulation, which results in the intravascular formation of fibrin and ultimately thrombotic occlusion of small and midsize vessels. "Here we report a case of TMA that followed disseminated intravascular coagulation (DIC) due to severe infection in a patient with a reduced ADAMTS-13 activity level." (PMID 24279773, 2013). "Our objectives were to assess the clinical significance, prognostic value and pathophysiology of ADAMTS13 deficiency in patients with septic shock with and without disseminated intravascular coagulation (DIC)." (PMID 24238574, 2013). "Later, it has been shown that association of functional deficiency of ADAMTS-13 and septic shock is independent of disseminated intravascular coagulation (DIC) and that ADAMTS-13 functional deficiency is a prognostic factor for mortality in septic shock patients." (PMID 28775254, 2017).